CD4 (CD4 molecule)
Diseases named in the same sentence as CD4 in open-access papers (continued):
Sharing a sentence is not in itself a finding about the gene and the disease.
hypothyroidism (43 papers, 2007 to 2025). Abnormally low levels of thyroid hormone. "Examples of significant associations for fetal cell types include Graves’ disease and hypothyroidism, and both were significantly associated with T lymphocyte 1 (CD4+)." (PMID 36232752, 2022). "On multivariate analysis, however, the same authors found that only stavudine treatment and low CD4 cell count were statistically associated with hypothyroidism." (PMID 27200374, 2016). "In our study, lower CD4 cell counts were associated with hypothyroidism in bivariate analysis, which may be a result of HIV infection itself being associated with thyroid dysfunction." (PMID 24194919, 2013). "The prevalence of overt hypothyroidism affects 2.5% to 3% of HIV patients, while patients with CD4 counts under 200 cells/mm3 show increased risk." (PMID 41301708, 2025). "The comparison between the hypothyroidism group and the healthy controls showed valid differences in the following immune cell types: naive CD4+T cells, naive B cells, CD8+T cells and memory B cells." (PMID 39872521, 2024). "Both pSS and hypothyroidism seem to share common pathophysiological characteristics; a CD4+ T-cell infiltration with the same histocompatibility antigens (HLA class 2)." (PMID 33917955, 2021). "The mean CD4 cell count was significantly lower in patients with hypothyroidism (372 ± 331/μL) than in the other patients (P < 0.05)." (PMID 27200374, 2016). "Furthermore, the study reported an association between NADCs and older age, co-infections, renal disease, hypothyroidism, and high-CD4+ T-cell count." (PMID 41301708, 2025). "Hypothyroidism was correlated with CD4 count and viral load." (PMID 31015954, 2019). "This difference may be because of low CD4 count increasing the likelihood of hypothyroidism." (PMID 41301708, 2025). "Several studies have shown the inverse correlation between the lymphocytes T CD4+ (CD4) counts and serum TSH levels, emphasizing the trend for hypothyroidism as HIV disease progression in both adults and pediatric cases." (PMID 36136821, 2022). "The purpose of this study was to analyze the relationship between T cell subsets (CD3+, CD4+, CD8+, and CD4+/CD8+), B cells (CD19+), and NK cells (CD56+) with radiation-induced hypothyroidism." (PMID 32461982, 2020). "In our study, CD4 cell count was lower in patients with overt hypothyroidism than in those without overt hypothyroidism, indicating that FT3 and FT4 levels were related to the progression of HIV infection to some degree." (PMID 27200374, 2016).
juvenile idiopathic arthritis (43 papers, 2005 to 2024). Juvenile idiopathic arthritis (JIA) is the term used to describe a group of inflammatory articular disorders of unknown cause that begin before the age of 16 and last over 6 weeks. "Further, the presence of a small subset of peripheral blood CD4+ T cells with similar characteristics to synovial CD4+ T cells is correlated with both disease activity and resistance to therapy in juvenile idiopathic arthritis (JIA)." (PMID 38817613, 2024). "The rs2239316 of CBP gene is associated with IL32 CpG methylation in CD4+ and CD8+ T cells, which in turn is associated with juvenile idiopathic arthritis." (PMID 38540428, 2024). "So far, there is only 1 published study that attempted to observe differences at the interaction level between patients and healthy controls in CD4+ T cells from juvenile idiopathic arthritis patients." (PMID 36281738, 2023). "Proinflammatory CD4+ cells with a similar BHLHE40+ phenotype have been identified in the joints of patients with juvenile arthritis and these cells expressed GM-CSF, TNF-α, and IFN-γ." (PMID 37751304, 2023). "CD4+ T cells of patients with active juvenile idiopathic arthritis (JIA) showed different transcriptional profiles compared to patients in remission and healthy controls, which were associated with differences in chromatin organization, and potentially, in occupancy of CTCF binding sites." (PMID 35222432, 2022). "In addition, it efficiently drives the differentiation of CD4+CD25− T cell clones derived from juvenile idiopathic arthritis patients into CD4+CD25high Tregs." (PMID 28194152, 2017). "In addition, in 2011, they demonstrated that CD4+CD161+T cells can shift from Th17 to the Th17/Th1 or even Th1 phenotype in SF of patients with juvenile idiopathic arthritis (JIA)." (PMID 28698517, 2017). "Finally, T cell clones expressing CD4 and CD8α have also been generated from a patient with lepromatous leprosy and from joint fluid of patients with juvenile rheumatoid arthritis." (PMID 23844100, 2013). "To date, analysis of juvenile idiopathic arthritis (JIA) immune pathology has concentrated on the contribution of CD4+ T cells; we have previously identified an expansion of Th17 cells within the synovial fluid (SF) of JIA patients." (PMID 30350355, 2019). "Research on CD4+CD25high regulatory T cells in juvenile idiopathic arthritis (JIA) has revealed distinct abnormalities in function and distribution in various disease subtypes." (PMID 19046457, 2008). "A similar subpopulation of γδ T cells was found to be increased in synovial fluid and blood of patients with juvenile idiopathic arthritis, which expressed IFN-γ and TNF-α to the same degree as CD4+ T cells." (PMID 38743491, 2024). "The frequencies of PD-1hiHLA-DR+CD4+ T cells in the SF of patients with ARLA were found to be significantly higher compared with age-matched patients with various subtypes of juvenile idiopathic arthritis (JIA), which served as disease controls." (PMID 38963700, 2024). "Furthermore, CD4+ T cells from patients with juvenile idiopathic arthritis (JIA), the most common autoimmune rheumatic disease of childhood, showed reduction of IL-32 through DNA methylation." (PMID 27182285, 2016). "Higher RORC expression of CD4+ T cells was described in early RA and juvenile idiopathic arthritis but not in PsA." (PMID 29670615, 2018). "In juvenile idiopathic arthritis, gp130 expression was reduced in monocytes and dependent on p38 MAPK activation while it was increased in CD4+ T cells in synovial tissue (but not in synovial fluid)." (PMID 28861079, 2017). "In this study, we report that, unlike in peripheral blood, CD4+ T cell expression of CD25 and FOXP3 is frequently dissociated at the inflamed site in patients with juvenile idiopathic arthritis, which led us to question the stability of human Tregs in chronic inflammatory environments." (PMID 25092890, 2014).
osteoporosis (43 papers, 2008 to 2026). A condition of reduced bone mass, with decreased cortical thickness and a decrease in the number and size of the trabeculae of cancellous bone (but normal chemical composition), resulting in increased fracture incidence. "A CD4 count ≥500 cells/mm3 (p < 0.001) and higher BMI (p = 0.008) were associated with reduced odds of osteoporosis." (PMID 41007865, 2025). "It has been demonstrated that RA patients with concurrent bone loss have the highest levels of CD4+CD28− T cells when compared to patients with osteoporosis and those with normal bone mass." (PMID 38473934, 2024). "The expansion of the senescent CD4+ T cell population has been associated with increased bone loss and support of the early development of osteoporosis in RA." (PMID 32190092, 2020). "Neurocognitive dysfunction, obstructive pulmonary disease, and osteoporosis, have also been linked to low nadir CD4+ T-cell counts." (PMID 30240419, 2018). "As suggested previously, CD4 cell counts > 500 c/microL may be a proxy of increasing age, associated with age-related conditions, including osteoporosis and low BMD." (PMID 38140615, 2023). "Therefore, increased bone resorption led to osteoporosis and increased risk of bone fracture in CD4-CKO mice." (PMID 34764263, 2021). "Besides, it has been demonstrated that senescent CD4+ T-cells were increased in patients with severe disease manifestations, and at the same time, these patients were at an increased risk of osteoporosis." (PMID 29472917, 2018). "Interestingly, this CD4+ immune phenotype was independently associated with osteopenia/osteoporosis in the multivariate logistic regression analysis." (PMID 23448662, 2013). "Next, we assessed whether BMMSC deficiency contributed to the osteoporosis phenotype in immunocompromised mice receiving CD4+CD25−CD45RB+hi T cells." (PMID 18612428, 2008). "In our study, osteoporosis and osteopenia were associated with age > 40 years, higher levels of VL-HIV ( > 10000 copies/mL), nadir CD4 + level <200 cells/mm3, prolonged ART exposure and TDF containing regimens." (PMID 41007865, 2025). "Among patients with a nadir CD4 + count <200 cells/mm3, 62 (91.1%) had osteopenia or osteoporosis, compared to 25 (65.8%, 25/38) of patients with nadir CD4 + ≥200 cells/mm3." (PMID 41007865, 2025). "It was observed that the awareness level of osteoporosis was lower among individuals with low educational level, CD4 count<200/mm3, and older age." (PMID 40105551, 2025). "Specifically, those with pre-treatment CD4 levels<200/mm3 and lower educational levels showed the lowest awareness levels of osteoporosis." (PMID 40105551, 2025). "Patients with pre-treatment CD4 counts<200/mm3 showed significantly lower osteoporosis awareness and knowledge levels based on OAS and OKAT results (p<0.001)." (PMID 40105551, 2025). "The study also aimed to evaluate potential differences and correlations in osteoporosis knowledge and awareness levels based on age, gender, educational level, treatments used, viral load, and CD4 count among HIV patients." (PMID 40105551, 2025). "In patients with a pre-treatment CD4 count<200/mm3, both the awareness and knowledge levels of osteoporosis were significantly lower." (PMID 40105551, 2025). "DAAM2 serves as a pivotal downstream effector for SIRT1 to exert immune-regulatory effects in the bone microenvironment; thus, targeting DAAM2 can treat osteoporosis by increasing CD4+ CTL responses." (PMID 40714829, 2025). "In particular, patients with a pre-treatment CD4 count<200/mm3 and those with lower education levels were found to have the lowest awareness level of osteoporosis." (PMID 40105551, 2025). "Patients with a pre-treatment CD4 count<200/mm3 had significantly lower levels of both osteoporosis awareness and knowledge (p<0.001)." (PMID 40105551, 2025). "In various diseases such as RA, juvenile idiopathic arthritis, osteomyelitis, and osteoporosis, there is often an elevated presence of prematurely senescent CD4+CD28− T cells." (PMID 38473934, 2024).
osteoporosis (continued). "Radiographic and histological analysis showed abolition of structure damage, new bone formation, and osteoporosis in CD4-CKO mice treated with sonidegib." (PMID 34764263, 2021). "In this study, we reported ectopic new bone formation and bony fusion, as well as osteoporosis, in mature CD4-CKO mice." (PMID 34764263, 2021). "Osteoporosis condition maintained lower number of CD4+Foxp+ Treg but higher proportion of CD4+IL-17+ Th17 cells as compared to sham treatment." (PMID 33109775, 2020). "Treg cells (both CD4+ and CD8+) have long been associated with bone protective functions, whereas Th17 has now been associated with inflammatory bone loss in RA, osteoporosis etc." (PMID 29410520, 2018). "In the present study we observed an enhanced level of CD4+CD25+CD127− Treg cells in women with osteoporosis." (PMID 28696349, 2017). "Taken together, the data indicated that both impaired BMMSCs and activated osteoclast activity in CD4+CD25−CD45RB+hi T cell-treated OVX-immunocompromised mice contributed to the osteoporosis phenotype." (PMID 18612428, 2008). "Notably, women with osteoporosis exhibited significantly lower current CD4+ T-cell counts (268.4 ± 180.5 cells/μL) compared to those with normal BMD." (PMID 42123655, 2026). "The obtained findings have suggested the potential of NLRC3 to attenuate osteoclastogenesis, thus promoting CD4+ T cell functions and their ability to recruit CD11bhiLy6Chi inflammatory monocytes into the bone marrow; thereby, restricting osteoporosis progression." (PMID 38436712, 2024). "Moreover, gut dysbiosis and increased intestinal permeability reported in osteoporosis induce activation of osteoclastogenic CD4+ T cells over-producing Rank-L and Tnf-α." (PMID 36848406, 2023). "Treg cells (both CD4+ and CD8+) are associated with bone protective functions, whereas Th17 has now been associated with inflammatory bone loss in RA, osteoporosis etc.." (PMID 29955622, 2018). "Were CD4+CD25+Foxp3+ Tregs involved in the development of osteoporosis?" (PMID 30406140, 2018). "The CD4+CD127-CD25+ natural Treg cell levels were increased in women affected by osteoporosis (3." (PMID 28696349, 2017). "A low BMD in the setting of HIV infection has been commonly ascribed to traditional risk factors (such as low BMI, smoking and older age) for osteoporosis and factors specific to HIV-infection such as the ART regimen used, initiation of ART and CD4 count at initiation of ART." (PMID 26633015, 2015). "Interestingly, in the multivariate logistic regression analysis that was adjusted for demographics and HIV- and HAART-related parameters, a higher frequency of activated CD4+/CD8+ T-cells was an independent predictor of osteopenia/osteoporosis." (PMID 23448662, 2013). "OVX-immunocompromised mouse is an established model with inducible osteoporosis phenotype that allows testing whether CD4+CD25−CD45RB+hi T cell can induce osteoporosis like bone density alteration in vivo." (PMID 18612428, 2008). "Apart from that, CD4+CD28- T cells have also been reported in HIV-infected individuals and lupus erythematosus-affected patients, in which their activity could explain the increased risk of developing osteoporosis observed in these diseases." (PMID 34341698, 2021). "Therefore, the expansion of peripheral senescent CD4+ T cells may impact bone mineral density and are negatively related to osteoporosis." (PMID 32190092, 2020). "Therefore, in this study we applied a widely used T-cell adoptive transfer system in mice to elucidate the association between CD4+CD45RB+hi T cells and BMMSCs, adding a potential mechanism that may contribute to the bone phenotype in osteoporosis patients." (PMID 18612428, 2008). "During osteoporosis, CD4+CD28- T lymphocytes expressed higher levels of TNF-α and intensely induced the activation of TRAP in osteoclasts as compared with CD4+CD28+ T lymphocytes." (PMID 34341698, 2021).
osteoporosis (continued). "This study aims to demonstrate the efficacy of RMF in AS-like mice generated by CD4-CKO gene editing, which exhibits the formation of ectopic extra bone, bone fusion, and osteoporosis, all of which result in spinal ankylosis and potentially lifelong disability." (PMID 37048045, 2023). "Finally, even though our study population had few specific inclusion criteria, our results may not be broadly applicable to all PLWH, as shown by the observation that some expected variables did not associate with osteoporosis, such as smoking, alcohol, and CD4 nadir." (PMID 37225667, 2023). "Furthermore, our MR results highlighted the contribution of CD39-positive cell (e.g., CD39+ CD4+ %CD4+, CD39+ CD8br %T cell, and CD39+ resting Treg %CD4 Treg) in exacerbating the progress of osteoporosis." (PMID 36341399, 2022). "Similarly, CD4+CD28− T lymphocytes generated during osteoporosis express higher levels of TNF-α and have the capacity to induce TRAP with greater intensity in osteoclasts compared to CD4+CD28+ T lymphocytes." (PMID 35269683, 2022). "ERβ expression in CD4+ T cells was required for DHEA, a hormone upstream of testosterone and estrogen,-mediated suppression of Th17 cells and EAE, and estrogen suppressed IL-17-mediated osteoclast differentiation which is important in osteoporosis." (PMID 31849948, 2019). "Additionally, 41.8% had CD4 counts ≤200/μL, compared to 18.0% in the non-osteopenia/osteoporosis group (p = 0.005)." (PMID 41007865, 2025).
severe combined immunodeficiency (43 papers, 2011 to 2025). Severe combined immunodeficiency (SCID) comprises a group of rare monogenic primary immunodeficiency disorders characterized by a lack of functional peripheral T lymphocytes resulting in early-onset severe respiratory infections and failure to thrive. "Genetic studies of patients with combined immunodeficiency (CID) with predominant CD4 cell deficiency have revealed mutations in genes encoding regulatory factors of the expression of MHC class II molecules such as CIITA, RFXANK, RFX5 or RFXAP." (PMID 25205547, 2014). "The absence or a very low proportion of naïve CD4 T cells is one of the diagnostic criteria for severe combined immunodeficiency (SCID), the most severe form of combined immunodeficiency." (PMID 39946072, 2025). "One patient of group 3 (11%) and 6 of group 4 (35%) had a severe reduction in CD4+ (<200 cells/mm3) and/or naïve CD4+ naive (20 cells/mm3), thus fulfilling the criteria for the diagnosis of Late-Onset Combined Immunodeficiency (LOCID)." (PMID 37304298, 2023). "The ESID 2014 and ICON 2016 criteria exclude patients with severe T cell defects, who were deemed to have late onset combined immunodeficiency (LOCID) based on reduced naïve CD4+ T cell proportions (<10% CD4+ T cells)." (PMID 35116031, 2021). "These updated criteria enable the exclusion of patients with combined immunodeficiency (CID) on the basis of demonstration of severe reductions in naive CD4 T cells." (PMID 31803177, 2019). "A previous study showed that CD4+ cells extracted from curdlan-induced SpA mice transferred SpA features to mice with severe combined immunodeficiency (SCID)." (PMID 30630513, 2019). "Mucocutaneous candidiasis, on the other hand, is a frequent complication in AIDS patients displaying low CD4+ T cell counts as a consequence of the viral infection and in severe combined immunodeficiency (SCID) patients with more general T cell defects." (PMID 26274976, 2015). "In severe combined immunodeficiency mice reconstituted with CD4+CD45RBhigh T cells, the injected ova-Treg cells were detected in inflamed tissue after 4 weeks, but not later." (PMID 24886976, 2014). "Furthermore, CD4+CD25+ Tregs can promote the differentiation of M2 macrophages in vivo by transferring directly into the peritoneal cavity of severe combined immunodeficiency mice." (PMID 32565732, 2020). "CD4+ T cells from ApoE-/- mice were transferred to ApoE-/- mice crossed with severe combined immunodeficiency (SCID) strains of mice, leading to greatly increased fatty streak lesions compared to immunocompetent ApoE-/- mice." (PMID 39399488, 2024). "However, only four patients displayed a severe reduction in CD4+ (<200 cells/mm3) and/or CD4 naive cells (20 cells/mm3), thus fulfilling the criteria for the diagnosis of Late-Onset Combined Immunodeficiency (LOCID): 3/17 patients in the NR group, 1/18 in the IgG-R and none in IgG/igA-R group." (PMID 35741048, 2022). "Moreover, depletion of MMTV Sag-activated TCR-Vβ subsets affected the ability of transferred activated CD4+ T cells to induce disease in mice with severe combined immunodeficiency (SCID)." (PMID 39817448, 2025). "In this model CD4+ T cells from immunocompetent mice are adoptively transferred into severe combined immunodeficiency (SCID) mice, lacking T cells." (PMID 32076420, 2020). "Loss of Zap70 in humans leads to Severe Combined Immunodeficiency (SCID) characterized by the absence of CD8 T cells and the presence of non-functional CD4 T cells." (PMID 24596147, 2014). "In line with their potential protective roles, adoptive transfer of CD4+ T cells into TBEV-infected Severe Combined Immunodeficiency (SCID; no T or B cells) mice was demonstrated to protect against lethal disease." (PMID 38318179, 2024).